MEIS2 (Meis homeobox 2)
Diseases named in the same sentence as MEIS2 in open-access papers (continued):
Sharing a sentence is not in itself a finding about the gene and the disease.
Alzheimer disease (1 paper, 2025). A progressive, neurodegenerative disease characterized by loss of function and death of nerve cells in several areas of the brain leading to loss of cognitive function such as memory and language. "Additionally, the orthologs of nhr-25(NR5A1 and NR5A2) and unc-62 (MEIS1, MEIS2, MEIS3) were linked to aging-related diseases such as dementia and Alzheimer’s disease." (PMID 40766245, 2025).
bladder cancer (1 paper, 2020). "Meis2 was also reported as overexpressed in bladder cancer tissue when compared with normal adjacent tissue." (PMID 33402862, 2020). "MEIS2 has been shown to induce metastasis in bladder cancer." (PMID 33402862, 2020). "Moreover, Meis2 knockdown significantly inhibits the migration and invasion capacities of bladder cancer cells." (PMID 33402862, 2020). "Polypyrimidine tract binding protein 1, is a protein that has a function bladder cancer metastasis, and controls Meis2 and pyruvate kinase alternative splicing via direct binding to specific introns of these mRNA transcripts, contributing to bladder cancer development." (PMID 33402862, 2020).
calcific aortic valve disease (1 paper, 2024). "Recent research further highlights MEIS2’s role in calcific aortic valve disease (CAVD), where its inhibition promotes osteoblastic transdifferentiation and reduces Notch1 and Twist1 expression, making MEIS2 a potential target for CAVD prevention." (PMID 39758840, 2024).
cataract (1 paper, 2020). Partial or complete opacity of the crystalline lens of one or both eyes that decreases visual acuity and eventually results in blindness. "Transfection studies of a human LEC-line (HLE-B3) and mouse capsular-bag LECs have further revealed a negative correlation between miR-204 and Meis2 transcript levels consistent with a role for miR-204 regulation in lens development and congenital cataract pathogenesis." (PMID 32070426, 2020).
colon cancer (1 paper, 2020). "Experimental evidences support the role of MEIS2 as oncogene in colon cancer tissue and the role of tumor suppressor of has-miR-192." (PMID 32938402, 2020).
colorectal adenocarcinoma (1 paper, 2021). The most common type of colorectal carcinoma. "The cBioPortal database was used to analyze the mutations of seven genes, which showed that E2F3, ETS2, HLF, HSF4, KLF4, MEIS2, and TCF7L1 were altered in 8, 8, 6, 6, 5, 9, and 6% of 524 colorectal adenocarcinoma patients separately." (PMID 34603375, 2021).
colorectal adenoma (1 paper, 2021). An adenoma that arises from the colon or rectum. "Notably, six DE-TFs, DACH1, GTF2IRD1, MEIS2, NR3C2, SOX9, and SPIB, were identified as having a dynamic signature along the colorectal adenoma-carcinoma sequence." (PMID 34094897, 2021).
diabetes (1 paper, 2024). "Of particular alert, several transcription factors were dynamically altered with the progression of diabetes, including Meis homeobox 2 (Meis2), Forkhead box P1 (Foxp1), and CCAAT enhancer binding protein beta (Cebpb)." (PMID 39475009, 2024). "Contrary to Meis2, Foxp1, and Cebpb, the expression of Ets1 in endothelial cells gradually declined with the progression of diabetes, with overtly lower levels in clusters 12 and 26 compared with other clusters." (PMID 39475009, 2024).
gastric cancer (1 paper, 2022). A primary or metastatic malignant neoplasm involving the stomach. "Collectively, our study demonstrated that MiR-18 promoted gastric cancer stemness by targeting Meis2 to suppress HMGB3 expression." (PMID 35416122, 2022). "To further verify that miR-18 targets Meis2 to promote the stemness of gastric cancer cells, we chose the luciferase reporter assay for confirmation." (PMID 35416122, 2022). "Furthermore, we also found that the low-expressed oncogene HMGB3 is involved in this miR-18/Meis2 axis to further promote the stemness of gastric cancer cells." (PMID 35416122, 2022). "Therefore, we speculate whether miR-18 promotes the stemness of GC cells by targeting Meis2 to up-regulate the expression of HMGB3 in gastric cancer." (PMID 35416122, 2022).
glioblastoma (1 paper, 2020). The most malignant astrocytic tumor (WHO grade IV). "Meis2 has a high expression profile in cholangiocarcinoma, glioblastoma, brain lower grade glioma, pancreatic adenocarcinoma, liver hepatocellular carcinoma, skin cutaneous melanoma, stomach adenocarcinoma, and thymoma." (PMID 33402862, 2020).
heart failure (1 paper, 2024). Inability of the heart to pump blood at an adequate rate to meet tissue metabolic requirements. "After intersecting the results of the three algorithms, we obtained four down-regulated key aging genes in heart failure, namely BCL6, EIF4EBP1, MEIS2, and SMARCA2." (PMID 38686376, 2024).
hypoglossia (1 paper, 2020). "Thus, failed medio-lateral patterning in Meis2 mutants at E10.5 leads to abnormal differentiation of tongue-specific NCCs and hypoglossia." (PMID 32616504, 2020).
imbalance (1 paper, 2022). "We therefore cannot fully exclude that Meis2 recombination also occurs in some of these central neuronal populations that somehow participate in the autonomic imbalance we report in Isl1+/CRE::Meis2LoxP/LoxP mice." (PMID 36418415, 2022).
lung carcinoma (1 paper, 2017). "In the present study, we found lung cancer specific hypermethylation of PAX5 and MEIS2." (PMID 28634396, 2017).
lung fibrosis (1 paper, 2023). "Both PITX2 and MEIS2 were upregulated hit genes in the enrichment of “positive regulation of myoblast proliferation” in AA-NL, a biological process observed during lung fibrosis." (PMID 36835058, 2023).
medulloblastoma (1 paper, 2011). A malignant, invasive embryonal neoplasm arising from the cerebellum. "Thus, MEIS2 might be necessary to specify the binding and/or biological function of OTX2 in medulloblastoma." (PMID 22016811, 2011).
mesothelioma (1 paper, 2022). A usually malignant and aggressive neoplasm of the mesothelium which is often associated with exposure to asbestos. "HAND2 expression coincided with differential expression of the previously mesothelium- and mesothelioma-associated genes MSLN and WT1, as well as with GATA5 and MEIS2." (PMID 35354817, 2022).
metastatic diseases (1 paper, 2023). "In addition, it has been reported that MEIS2 may be associated with certain metastatic diseases." (PMID 37621680, 2023).
microcephaly (1 paper, 2023). A congenital or acquired developmental disorder in which the circumference of the head is smaller than normal for the person's age and sex. "In a recent study, 8 of 17 patients (47%) with a 15q14 deletion presented with microcephaly compared to 2 of 11 patients (18%) with de novo MEIS2 variants, suggesting MEIS2 as a responsible gene for microcephaly." (PMID 38094004, 2023). "Given that microcephaly is more prevalent in 15q14 deletion than in de novo variants or intragenic deletions in MEIS2, it is possible that unidentified variants in a nearby region have a synergistic influence on the phenotype when combined with MEIS2 loss or variants." (PMID 38094004, 2023). "Conditional depletion of Meis2 in the forebrain would be a valuable experiment to further elucidate the role of Meis2 in microcephaly." (PMID 38094004, 2023). "In this study, I focus on several homeobox genes (ARX, LHX2, MEIS2, NKX2-1, OTX1, OTX2, and PAX6) implicated in the pathogenesis of microcephaly." (PMID 38094004, 2023). "Interestingly, microcephaly has been observed (not fully penetrant) in patients with chromosome 15q14 microdeletions, which encompasses MEIS2 and is a well-known chromosomal cause of palatal defects co-occurring with congenital heart defects and intellectual disability." (PMID 38094004, 2023).
microphthalmia (1 paper, 2012). Congenital or developmental anomaly in which the eyeballs are abnormally small. "For example, Meis homeobox 2 (MEIS2) modulates PAX6 transcription activity, and in madaka fish morpholino-mediated ablation of miR-204 targeting Meis2 results in an eye phenotype characterized by microphthalmia, abnormal lens formation, and altered dorsoventral patterning of the retina." (PMID 22550392, 2012).
myeloid leukemia (1 paper, 2020). A clonal proliferation of myeloid cells and their precursors in the bone marrow, peripheral blood, and spleen. "In addition, Meis2 is overexpressed in myeloid leukemia mice, resulting in the conclusion that MEIS1 and MEIS2 may have a parallel function in myeloid leukemia." (PMID 33402862, 2020).
Neurodevelopmental delay (1 paper, 2024). "In humans, at least 17 different mutations in the Meis2 gene have been associated with neurodevelopmental delay, emphasizing its essential function in neuronal differentiation." (PMID 38386003, 2024).
pancreatic adenocarcinoma (1 paper, 2020). "Meis2 and Meis3 expression were increased in pancreatic adenocarcinoma." (PMID 33402862, 2020).
pancreatic endocrine neoplasms (1 paper, 2020). "On the other hand, global gene expression analysis of nonmetastatic pancreatic endocrine neoplasms and metastatic pancreatic endocrine neoplasms revealed that Meis2 was downregulated in metastatic pancreatic endocrine neoplasms." (PMID 33402862, 2020).
Parkinson (1 paper, 2023). "A decrease in gene sets related to oxidative phosphorylation, mitochondrial function, and Parkinson-associated genes was seen in Meis2 interneurons, possibly underlying cell type-specific vulnerability." (PMID 37308288, 2023).
Pc (1 paper, 2025). "These epithelial changes probably require additional Meis2-dependent intermediate steps, which might act either in parallel with or downstream of dermal WNT signaling to induce Pc formation." (PMID 40183774, 2025).
Prader-Willi syndrome (1 paper, 2017). "MEIS2 maps to 15q14 distal to the Angelman/Prader-Willi syndromes genomic region on 15q11.2q12 and the CHRNA7 gene on 15q13.3 (located 5 Mb from MEIS2)." (PMID 28934986, 2017).
thymoma (1 paper, 2020). A neoplasm arising from the epithelial cells of the thymus. "Meis1, Meis2, and Meis3 were upregulated in lymphoid neoplasm diffuse large B-cell lymphoma and thymoma cancers." (PMID 33402862, 2020).
cancer (29 papers, 2010 to 2025). A tumor composed of atypical neoplastic, often pleomorphic cells that invade other tissues. "MEIS2 has an important role in development and organogenesis, and is implicated in the pathogenesis of human cancer." (PMID 25210800, 2014). "Some evidences suggest that MEIS2 is associated with some cancers progression." (PMID 38711262, 2024). "We speculate that the SNP could be situated in a regulatory region of the MEIS2 gene that may modify its expression and in this way alter cancer risk and prognosis." (PMID 22125638, 2011). "The expression of MEIS2 is deregulated in some cancers, and MEIS2 functions differently in cancers of different tissue (organ) origins." (PMID 38711262, 2024). "The discrepancy of MEIS2 expression and role in different cancers suggests that MEIS2 is not a universal oncogene or tumor suppressor, and the role of MEIS2 in cancer depends on the signaling networks that MEIS2 is involved in." (PMID 38711262, 2024). "The results showed that IL10 silence alleviated the effects of MEIS2 on mobility and proliferation rate of BC cells, indicating that MEIS2 mediated the proliferation rate and mobility of cancer cells through IL10." (PMID 38711262, 2024). "MEIS2 is a transcriptional regulator whose role in fibrosis has not been studied; however, it has been characterized in embryonic development and cancer." (PMID 36835058, 2023). "The Meis2 expression pattern in cancer tissues differs from that of Meis1, and it also differs in adult tissues." (PMID 33402862, 2020). "According to the GEPIA and BioGPS datasets, the expression of Meis1, Meis2, and Meis3 vary in different cancers." (PMID 33402862, 2020). "Differential hydroxymethylation is found in thousands of genes, most significantly in genes related to pancreas development or function (GATA4, GATA6, PROX1, ONECUT1, MEIS2), and cancer pathogenesis (YAP1, TEAD1, PROX1, IGF1)." (PMID 33077732, 2020). "On the other hand, tumor expression of MEIS2 confers a more indolent prostate cancer phenotype, with a decreased propensity for metastatic progression, suggesting cancer specific mechanisms." (PMID 30975979, 2019). "MEIS2 has been identified as one of the key transcription factors in the gene regulatory network in the development and pathogenesis of human cancers." (PMID 31623651, 2019). "On the other hand, genes responsible for the negative regulation of transcription including Meis homeobox 2 and C-terminal binding protein 2 were both up-regulated in L6 and L7 tomato extract treated cancer cells." (PMID 28448505, 2017). "Deregulation of Hox protein cofactors MEIS2, MEIS1 and Pbx1 are associated with cancer oncogenesis and tumor progression." (PMID 24391925, 2013). "Maybe it seems contradictory, the possible reason is that MEIS2 involves in more than one signal network, by which MEIS2 conducts its specific role in a certain cancer." (PMID 38711262, 2024). "Therefore, MEIS2 can be considered as one of the genes involved in neurodevelopmental disorders and cancers, such as those related to the RAS pathway genes or BAF complex genes." (PMID 39776641, 2024). "Meis2, a transcription factor, is a member of the Meis protein family that plays a vital role in regulating cell fate during cell proliferation and is related to the pathogenesis of human cancer." (PMID 35416122, 2022). "Recent efforts have identified MEIS2 as one of the key transcription factors in human cancers." (PMID 31623651, 2019). "Therefore, we hypothesized that MEIS2 affected cancer cell growth through regulating the expression of IL10." (PMID 38711262, 2024). "Therefore, further studies are needed to clarify the specific role of MEIS2 in cancer." (PMID 37621680, 2023). "Next, for determining which member contributed to the generally impaired expression of MEIS subfamily in cancers, we investigated the expression of MEIS1, MEIS2, and MEIS3 in multiple TCGA cancers." (PMID 35351858, 2022).
cancer (continued). "Among these, we identify a number of known cancer genes (i.e., FOXL2, RUNX1T1), transcription factors (i.e., MEIS2), as well as LHX1 and PAX6 (which are also recurrently affected by mutations)." (PMID 33741928, 2021). "Hypermethylation has already been reported for PAX5, KCNAB3, MEIS2 and GFRA3 in different cancer entities." (PMID 28634396, 2017). "This analysis validated the identification of genes that could be specific to cancer biology, such as IL7R, JUN, NR3C1 in Ba/Sq subtype, NPAS2, FOXQ1, GRHL3 in Luminal samples, or CDKN2C, FOXJ1, MEIS2, FGFR3 in both subtypes." (PMID 36944729, 2023). "In addition, five genes involved in the 47-mRNA metastasis-related model, including FABP4, GUCY2C, MEIS2, POU1F1, and SLC25A11 have been reported to be related to the metastasis of other human cancers." (PMID 33159021, 2020). "However, the exact role of MEIS2 in different cancers is not unified and seems to be tissue‐type dependent." (PMID 38711262, 2024).
tumor (22 papers, 2011 to 2025). "In present study, our studies demonstrate that the expression of MEIS2 in BC is associated with BC clinical stages and pathological grades, and MEIS2 functions as a tumor suppressor in BC." (PMID 38711262, 2024). "Depletion of Meis2 resulted in increased tumor growth over time in vivo, and was associated with increased expression of the tumorigenic genes cMYC and CD142." (PMID 35416122, 2022). "We identified MEIS2 as an early tumor initiation associated factor, as well as multiple novel MYCN-upregulated dependency genes." (PMID 34638267, 2021). "Prior studies implicated MEIS1 and MEIS2 as putative tumor suppressors in PrCa based upon clinical associations between retention of tumor expression and overall survival or risk of metastasis." (PMID 32553107, 2020). "Depletion of Meis1 and Meis2 in vivo may cause tumor growth and an increase in the expression of protumorigenic genes c-Myc and CD142." (PMID 33402862, 2020). "In addition, tumors from Aire−/− mice had lower levels of expression of Ptp4a1 and Meis2 which have been shown to promote tumor progression and are associated with poor survival." (PMID 32641748, 2020). "We found that MEIS2 knockdown significantly promoted MDA‐MB‐231 xenograft tumor growth in mouse models." (PMID 38711262, 2024). "The expression of MEIS2 in BC is significantly and reversely correlated with tumor pathological grades and BC differentiation." (PMID 38711262, 2024). "Consistently, comparative analysis of these patient‐derived datasets showed a reverse correlation between MEIS2 expression and BC tumor pathological grades." (PMID 38711262, 2024). "We found that overexpression of MEIS2 significantly suppressed BC xenograft tumor development in mouse models." (PMID 38711262, 2024). "The expression of MEIS2, FMN1 and CTDSPL2 proteins is associated with impaired renal function and can be regulated by tRF-5b, which can replace miR-458 during tumor suppression." (PMID 35409004, 2022). "Specifically, they reported a step-wise decrease in MEIS1 expression during PCa progression, but that knockdown of both MEIS1 and MEIS2 were necessary to suppress tumor development in vivo." (PMID 32681068, 2020). "We previously demonstrated that depletion of both MEIS1 and MEIS2 in LAPC4 cells was necessary to promote tumor xenograft growth." (PMID 32553107, 2020). "Most methylation probes exhibited strong discriminatory performance between tumor and normal tissue, with median AUC of 0.834 and probes within three genes—MEIS2, NRG1, and SRPX—exhibiting sensitivities greater than 90%." (PMID 30917865, 2019). "This analysis revealed significant differential methylation as well as downregulation of MEIS2, a homeobox gene previously investigated for its tumor suppressive role in PC initiation and progression." (PMID 31640805, 2019). "The tumor suppressor role of MEIS2 is partially mediated by downregulation of IL10." (PMID 38711262, 2024). "Our results indicate that MEIS2 might involve in the remodel of TME in tumor site, but whether MEIS2 affects other immune cells such as T cell in TME is also very interesting." (PMID 38711262, 2024). "Moreover, while Meis1, Meis2, and Pbx1 expressions are downregulated, Hoxa9 expression is upregulated during the tumor initiation and progression of PC." (PMID 33402862, 2020). "In PC, the high expression of Meis1 and Meis2 is required for the growth of the tumor." (PMID 33402862, 2020). "Thus, both MEIS1 and full-length MEIS2 are sufficient to slow PrCa cell proliferation and tumor growth via reduced G1/S phase transition and decreased migratory capacity." (PMID 32553107, 2020). "The results shown in this work underscore novel roles of MEIS2 in MM biology, as a regulator of cell growth and resistance to apoptosis, and describe a molecular pathway where its modulation could increase tumor recognition and killing by the immune system." (PMID 30975979, 2019). "Second, there may be MEIS2-specific functions that contribute to tumor suppression." (PMID 32553107, 2020).